POU2F2 (POU class 2 homeobox 2)
Description:
Transcription factor that specifically binds to the octamer motif (5'-ATTTGCAT-3'). Regulates IL6 expression in B cells with POU2AF1 (By similarity). Regulates transcription in a number of tissues in addition to activating immunoglobulin gene expression. Modulates transcription transactivation by NR3C1, AR and PGR. [Isoform 5]: Activates the U2 small nuclear RNA (snRNA) promoter.
Synonyms: Oct-2; OCT2; OTF2
Tractability: PROTAC: ubiquitination databases record sites on it; its protein half-life has been measured.
Target class: Transcription factor
Gene: Protein-coding gene on chromosome 19 (42,086,110 to 42,196,585, reverse strand). Ensembl gene ENSG00000028277.
Subcellular location: Cytoplasm; Nucleus
Subcellular location (Human Protein Atlas): Nucleoplasm; Vesicles
Pathways (Reactome):
Developmental Biology: Differentiation of naive CD4+ T cells to T helper 2 cells (Th2 cells)
Gene expression (Transcription): RNA polymerase II transcribes snRNA genes
Gene Ontology:
Molecular function: sequence-specific DNA binding; sequence-specific double-stranded DNA binding; DNA-binding transcription factor activity; DNA-binding transcription factor activity, RNA polymerase II-specific; RNA polymerase II cis-regulatory region sequence-specific DNA binding; transcription cis-regulatory region binding; DNA binding
Biological process: cellular response to virus; humoral immune response; positive regulation of interleukin-6 production; positive regulation of transcription by RNA polymerase II; regulation of transcription by RNA polymerase II; regulation of DNA-templated transcription
Cellular component: nucleoplasm; nucleus; chromatin; RNA polymerase II transcription regulator complex; cytoplasm
Genetic constraint (gnomAD): Loss-of-function variants: 9 observed, 56.38 expected, observed/expected ratio (o/e) 0.16, 90% interval 0.095 to 0.28. The upper end of that interval is the gene's LOEUF score, 0.28, which puts it in group 1 of 6, group 1 being the genes least tolerant of losing a copy. Missense variants: 577 observed, 749.84 expected, observed/expected ratio (o/e) 0.77, 90% interval 0.72 to 0.82. Synonymous variants: 292 observed, 316.64 expected, observed/expected ratio (o/e) 0.92, 90% interval 0.84 to 1.02.
Homologues: Orthologues: macaque POU2F2 (94% identical), pig POU2F2 (93% identical), rat Pou2f2 (93% identical), mouse Pou2f2 (91% identical), dog POU2F2 (91% identical), rabbit POU2F2 (88% identical), guinea pig POU2F2 (86% identical), chimpanzee POU2F2 (84% identical), tropical clawed frog pou2f2 (56% identical), zebrafish pou2f2b (55% identical), Caenorhabditis elegans ceh-18 (24% identical), Drosophila melanogaster vvl (21% identical), and 2 more. Paralogues in human: POU2F1 (49% identical), POU2F3 (35% identical), POU3F3 (23% identical), POU3F2 (21% identical), POU3F4 (21% identical), POU3F1 (20% identical), POU5F1 (18% identical), POU5F1B (18% identical), POU6F1 (18% identical), POU6F2 (18% identical), POU4F3 (17% identical), POU4F1 (17% identical), and 5 more.
Diseases named in the same sentence as POU2F2 in open-access papers:
POU2F2 is named in the same sentence as 69 diseases in open-access papers, as found by Europe PMC text mining. Sharing a sentence is not in itself a finding about the gene and the disease. The quoted sentences say what the papers report.
breast carcinoma (8 papers, 2013 to 2025). "Previous studies have demonstrated that these transcription factors play critical roles in various cancers; for example, HINFP shows significant regulatory effects in bladder cancer, POU2F2 is linked to lung cancer, and JUND and FOXC1 are key in colorectal and breast cancer, respectively." (PMID 40417238, 2025). "Transcription factors POU2F2, miR-548b-3p, and miR-206 regulate NAMPT expression in breast cancer cells." (PMID 37491379, 2023).
colorectal cancer (8 papers, 2022 to 2026). A primary or metastatic malignant neoplasm that affects the colon or rectum. "Recent investigations in colorectal cancer have unveiled the pivotal roles of AP1 and POU2F2 in OIS evasion, identifying the epigenetic memory of senescence-associated chromatin scarring (SACS) during colorectal cancer progression." (PMID 38795254, 2024).
lung carcinoma (7 papers, 2016 to 2025). "We then investigated the mechanisms underlying POU2F2 promoting the prolifetion, and motility of lung cancer cells in vitro." (PMID 33832481, 2021). "We found POU2F2 was highly expressed in human lung cancer tissues and cell lines, and associated with the lung cancer patients’ prognosis and clinical features." (PMID 33832481, 2021). "Furthermore, PIK3C2G, FIBIN, CHRNA1, NPNT, MEOX1, and POU2F2 linked obesity and lung cancer, while PTPRQ, SSUH2, CILP2, CDH2, ABCA12, CPXM1, and L1CAM linked hypertension and lung cancer." (PMID 36685671, 2023). "First, plv-POU2F2 plasmids were constructed and transfected into two types of lung cancer cells, including A549 and H1299 cells, respectively, to induce the overexpression of POU2F2 in these cells." (PMID 33832481, 2021). "Our previous data showed that POU2F2 promoted lung cancer cell proliferation, migration, and invasion in vitro." (PMID 33832481, 2021). "Further through Immunoblot, we found POU2F2 expression was upregulated in lung cancer tissues from three different patients, compared to their corresponding normal tissues." (PMID 33832481, 2021). "In this study, we noticed POU2F2 was highly expressed in lung cancer tissues, and importantly, we found POU2F2 affected the progression of lung cancer in vitro and in mice." (PMID 33832481, 2021). "Since POU2F2 was highly expressed in lung cancer tissues and correlated with the prognosis, we then detected its effects on the progression of lung cancer in vitro." (PMID 33832481, 2021). "Collectively, we thought POU2F2 was highly expressed in human lung cancer tissues and correlated with patients’ prognosis and clinical features." (PMID 33832481, 2021). "Collectively, these results showed that POU2F2 promoted tumor growth of lung cancer cells via AGO1 in mice." (PMID 33832481, 2021). "Through Kaplan–Meier survival analysis, we found the expression of POU2F2 was significantly correlated with the surviving fraction of lung cancer patients (p = 0.0385), suggesting the obvious correlation with prognosis." (PMID 33832481, 2021). "As a comparison, we found POU2F2 depletion inhibited the expression of AGO1 in two types of lung cancer cells." (PMID 33832481, 2021). "Immunoblot assays were performed to assess the expression levels of POU2F2 in human lung cancer tissues and cell lines." (PMID 33832481, 2021). "Immunohistochemical (IHC) assays were conducted to assess the expression of POU2F2 in human lung cancer tissues." (PMID 33832481, 2021). "To investigate the potential role of POU2F2 in the progression of lung cancer, we first assessed the expression levels of POU2F2 in lung cancer tissues and the adjacent tissues isolated from patients through IHC assays." (PMID 33832481, 2021). "We here found the involvement of AGO1 in lung cancer progression, and further confirmed that POU2F2 regulated lung cancer progression via AGO1." (PMID 33832481, 2021). "POU2F2 could function as a potential therapeutic target for lung cancer because it was significantly expressed in lung cancer cells." (PMID 37925496, 2023). "In summary, we noticed the high POU2F2 levels in human lung cancer tissues and cell lines." (PMID 33832481, 2021). "POU2F2 expression correlated with the prognosis and clinical features of lung cancer patients." (PMID 33832481, 2021). "Similarly, to the previous results, we noticed POU2F2 was upregulated in human lung cancer cell lines compared to the bronchial epithelial cell line." (PMID 33832481, 2021). "Then we explored whether POU2F2 promoted the proliferation, migration, and invasion of lung cancer cells via AGO1." (PMID 33832481, 2021). "POU2F2 promoted the proliferation, and motility of lung cancer cells via targeting AGO1 in vitro." (PMID 33832481, 2021). "We next explored whether POU2F2 was highly expressed in human lung cancer cell lines compared to normal bronchial epithelial cell lines." (PMID 33832481, 2021).
lung carcinoma (continued). "Interestingly, we found a transcription factor, POU2F2, was high expression in human lung cancer tissues and cell lines." (PMID 33832481, 2021). "Therefore, we thought POU2F2 promoted the proliferation, migration, and invasion of lung cancer cells via targeting AGO1." (PMID 33832481, 2021). "Herein, we found the high POU2F2 expression in human lung cancer tissues and cells." (PMID 33832481, 2021). "We found POU2F2 was highly expressed in lung cancer cells and confirmed the involvement of POU2F2 in lung cancer progression, and thought POU2F2 could act as a potential therapeutic target for lung cancer." (PMID 33832481, 2021). "Importantly, we noticed the high expression levels of POU2F2 in human lung cancer tissues, compared to normal tissues." (PMID 33832481, 2021). "We further demonstrated POU2F2 could promote the proliferation and motility of lung cancer cells through transcriptionally activating AGO1, and fascinate tumor growth of lung cancer cells in mice." (PMID 33832481, 2021). "Additionally, POU2F2 promoted tumor growth of lung cancer cells via AGO1 in vivo." (PMID 33832481, 2021). "Therefore, POU2F2 could have the potential to serve as a therapeutic target for lung cancer, which needs further study." (PMID 33832481, 2021). "In summary, POU2F2 could promote the expression of AGO1 in lung cancer cells." (PMID 33832481, 2021). "We therefore thought POU2F2 could act as a promising target for lung cancer." (PMID 33832481, 2021). "Therefore, POU2F2 depletion could inhibit the proliferation, migration, and invasion of lung cancer cells." (PMID 33832481, 2021). "However, when the sequence of site 1 was mutant, POU2F2 overexpression could hardly stimulate the luciferase activity of AGO1 in lung cancer cells, further confirming our conclusion." (PMID 33832481, 2021). "Four types of human lung cancer cell lines, including calu-3, calu-6, A549, and H1299, and a normal bronchial epithelial cell line BEAS-2B were used to detect the expression of POU2F2 in these cell lines via Immunoblot assays." (PMID 33832481, 2021). "We also found POU2F2 could promote the proliferation, and motility of lung cancer cells via AGO1, and contribute to tumor growth of lung cancer cells in mice." (PMID 33832481, 2021). "Next we should detect whether POU2F2 and POU2F1 have synergistic effect in the progress of lung cancer." (PMID 33832481, 2021). "Importantly, we found the expression of POU2F2 was obviously correlated with the tumor size (p = 0.021), TNM stage (p = 0.024), and nodal status (p = 0.047) of patients with lung cancer." (PMID 33832481, 2021).
glioblastoma (5 papers, 2021 to 2024). The most malignant astrocytic tumor (WHO grade IV). "POU2F2 encodes Oct-2 which is essential in immune response and its over-expression has been implicated in several cancers, including glioblastomas, breast, and pancreatic cancers." (PMID 39272962, 2024). "Here, we identified that the highly expressed POU2F2 significantly correlated with poor prognosis of glioblastoma (GBM) patients." (PMID 33931589, 2021). "Recent studies have shown that POU2F2 could promote glioblastoma progression by regulating glycolysis." (PMID 35757392, 2022).
colon cancer (4 papers, 2019 to 2024). "This NK signature consists of SLC2A3 and POU2F2, can predict both the prognosis of colon cancer patients and the efficacy of immunotherapy." (PMID 38561388, 2024).
gastric cancer (4 papers, 2019 to 2021). A primary or metastatic malignant neoplasm involving the stomach. "POU2F2 was highly expressed in multiple types of tumor tissues, such as gastric cancer and liver cancer." (PMID 33832481, 2021). "Recent studies have shown that POU2F2 also expressed in some solid tumors and provided the prognosis of cancer patients, including clear cell renal cell carcinoma, gastric cancer, and pancreatic cancer." (PMID 33931589, 2021). "Recent studies have uncovered the presence of Pou2f2 in several tumors including pancreatic and gastric cancers, the latter having a high frequency of invasiveness and metastasis." (PMID 31787878, 2019). "Interestingly, Pou2f2 has been identified in a Nf-kB/Pou2f2/Robo1/Slit2 signaling cascade that promotes metastasis in gastric cancer cells." (PMID 31787878, 2019). "POU2F2-oriented network could promote the metastasis of gastric cancer." (PMID 33832481, 2021). "POU2F2 functions as a bond to linking NF-κB and SLIT2/ROBO1 interaction network and promoting gastric cancer metastasis." (PMID 33931589, 2021).
cervical cancer (3 papers, 2022 to 2024). A primary or metastatic malignant neoplasm involving the cervix. "Long noncoding RNA ARAP1-AS1 promotes cervical cancer progression through the regulation of miR-149-3p and POU2F2." (PMID 35719192, 2022).
glioma (3 papers, 2020 to 2024). A benign or malignant brain and spinal cord tumor that arises from glial cells (astrocytes, oligodendrocytes, ependymal cells). "We found that POU2F2 was higher expressed in GBM than it in low grade gliomas, including astrocytoma and oligodendroglioma." (PMID 33931589, 2021).
lung adenocarcinoma (3 papers, 2017 to 2025). A carcinoma that arises from the lung and is characterized by the presence of malignant glandular epithelial cells. "The POU2F2 and TRIM28 co-expressed lncRNA landscape characterized here may shed light into normal biology and lung adenocarcinoma pathogenesis, and be valuable for discovery of biomarkers." (PMID 29127420, 2017).
neuroblastoma (3 papers, 2011 to 2021). Neuroblastoma (NB) is the most common solid, extracranial childhood tumor. "POU2F2 predicted the poor prognosis of patients with neuroblastoma and large cell lymphomas." (PMID 33832481, 2021). "We present eight genes (KRT19, PRKCDBP, SCNN1A, POU2F2, TGFBI, COL1A2, DHRS3 and DUSP23) that are methylated in neuroblastoma, most of them not previously reported as such, some of which also distinguish between biological subsets of neuroblastoma tumors." (PMID 21314941, 2011).
B Cell lymphoma (2 papers, 2018 to 2021). "Based on GSEA, we found that POU2F2 depletion led to lower expression of amount of glucose import genes in B Cell lymphoma cells." (PMID 33931589, 2021). "We found that PDPK1 (also known as PDK1) was downregulated after POU2F2 knockdown in B Cell lymphoma cells, that could interact with AKT and phosphorylated it at T308." (PMID 33931589, 2021).
Hypertension (2 papers, 2023). The presence of chronic increased pressure in the systemic arterial system. "In conclusion, the novel regulation of POU2F2 and CEBPB in VSMCs will help us understand the pathogenesis of hypertension and support the development of future treatments for hypertension." (PMID 36942826, 2023). "Elucidating the novel role of POU2F2 and CEBPB can assist our understanding of the pathogenesis of hypertension and supports the development of future treatments for hypertension." (PMID 36942826, 2023). "In this context, the additive effect of POU2F2 and CEBPB may be able to explain the progressive increase in BP during the development of hypertension." (PMID 36942826, 2023).
lymphoma (2 papers, 2017 to 2021). A malignant (clonal) proliferation of B- lymphocytes or T- lymphocytes which involves the lymph nodes, bone marrow and/or extranodal sites. "For example, several genes previously identified in other types of lymphomas, such as NOTCH1, POU2F2, CXCR4, and IGF1R, were affected by mutations." (PMID 28152507, 2017). "GSEA of previous microarray data GSE7929 showed POU2F2 might be involved in glycolytic reprogramming in lymphoma cells." (PMID 33931589, 2021).
malignant melanoma (2 papers, 2011 to 2021). "Furthermore, we identified POU2F2, IRF1, and FOSL2 as the most highly correlated TFs with CD274 expression in melanoma across all five datasets." (PMID 34503064, 2021).
Multiple Myeloma (2 papers, 2025). "According to the research results of cell type-specific regulatory activity, the most activated TFs in these myeloma cell subgroups included ETV7(C0 GNB2L1+ NK cells), TAF1(C1 RACK1+ NK cells), POU2F2(C2 HNRNPH1+ NK cells), and RUNX2(C3 ATP5E+ NK cells)." (PMID 40454289, 2025).
small cell lung carcinoma (2 papers, 2020 to 2021). Small cell lung cancer (SCLC) is a highly aggressive malignant neoplasm, accounting for 10-15% of lung cancer cases, characterized byrapid growth, and early metastasis. "The data exhibited that the expression of KLF5 was almost similar in 4–5 malignant tumor samples, while that of POU2F2 was upregulated only in small cell lung cancer samples." (PMID 34722892, 2021).
amebiasis (1 paper, 2022). A parasitic infectious disorder caused by amoebas. "However, some factors thought to be important for dcMO development (i.e., Flt3, Pou2f2, Pid1, and Hpgd) were strongly downregulated while their expression by monocytes from the amebiasis model was comparably higher." (PMID 36010615, 2022).
brain tumors (1 paper, 2021). "Knockdown of POU2F2 significantly suppressed the growth of brain tumors and increased the survival time of mice, and these effects were reversed by the recovered expression of PDPK1." (PMID 33931589, 2021).
Hyperkeratosis (1 paper, 2025). Hyperkeratosis is a histopathological term defining a thickened stratum corneum and may be present in many different skin conditions, with many possible overlaps. "Additionally, bioinformatic analysis revealed that on day 4 post-transplantation, the immune response was mainly suppressive, suppressing graft hyperkeratosis, which is a characteristic of rejection, and that Lcn2 and Pou2f2 further negatively regulated the immune response." (PMID 41221286, 2025).
lupus (1 paper, 2023). "POU2F2/OCT2, important for generation of ASCs; SWAP70, shown to influence ABC expansion; and AIM2, which positively regulated expansion of autoreactive B cells in a mouse lupus model, were increased in both blood and skin B cells in active cGVHD." (PMID 37129971, 2023).
osteoporosis (1 paper, 2022). A condition of reduced bone mass, with decreased cortical thickness and a decrease in the number and size of the trabeculae of cancellous bone (but normal chemical composition), resulting in increased fracture incidence. "Further work will focus on the exact contribution of NFIC, BACH1, CEBPB, and POU2F2 to osteoporosis pathogenesis." (PMID 35757392, 2022). "The core transcription factors in the ceRNA network, NFIC, BACH1, CEBPB, and POU2F2, might be related to osteoporosis." (PMID 35757392, 2022). "Furthermore, POU2F2 expression is related to fracture healing, and overexpression of POU2F2 promoted protein and mRNA expression of Colla1, Runx2, Osterix, and Osteocalcin in osteoporosis." (PMID 35757392, 2022). "There is no direct evidence that POU2F2 is involved in osteoporosis." (PMID 35757392, 2022).
prostate tumor (1 paper, 2017). "We report known prostate tumor regulatory drivers and nominate novel transcription factors (ERF, CREB3L1, and POU2F2), which are supported by functional validation." (PMID 28750683, 2017).
psoriasis (1 paper, 2022). An autoimmune condition characterized by red, well-delineated plaques with silvery scales that are usually on the extensor surfaces and scalp. "NFIC, NFYA, POU2F2, FOXA1 and SRF were discovered to be significant in psoriasis in our study after a gene-transcription factor regulatory network and several relevant transcription factors were evaluated." (PMID 36499614, 2022).
Sepsis (1 paper, 2024). Sepsis is defined as life-threatening organ dysfunction caused by a dysregulated host response to infection. "The expression of some of those genes (FCRL1, TNFRSF13C, CD22, CD79A, POU2F2) continue to be upregulated during sepsis recovery stage too." (PMID 38898888, 2024).